CAVIN1 (caveolae associated protein 1)
Diseases named in the same sentence as CAVIN1 in open-access papers (continued):
Sharing a sentence is not in itself a finding about the gene and the disease.
cardiac hypertrophy (2 papers, 2016). "PTRF/Cavin-1 deficiency shows reductions of caveolae and caveolin-3 (Cav3) protein expression in skeletal muscle, and Cav3 deficiency in the heart causes cardiac hypertrophy with loss of caveolae." (PMID 27612189, 2016). "To obtain further insights into caveola function in cardiomyocytes, we utilized PTRF−/− mice and found that PTRF/Cavin-1 deficiency induces down-regulated expression of caveola-associated proteins in the heart and cardiac hypertrophy accompanied by fibrosis." (PMID 27612189, 2016). "Thus, PTRF/Cavin-1 deficiency stimulates gene expression associated with cardiac hypertrophy and fibrosis." (PMID 27612189, 2016). "However, the specific impact of PTRF/Cavin-1 on the molecular mechanisms involved in cardiac hypertrophy and function remains to be determined." (PMID 27612189, 2016).
Hypoglycemia (2 papers, 2020 to 2022). A decreased concentration of glucose in the blood. "Insulin and glucagon signaling are both dramatically dampened in Cavin1−/− mice, the Cavin1 deficiency leads to lethal neonatal hypoglycemia." (PMID 35723340, 2022). "Cavin1 deficiency causes severe hypoglycemia, dampens the storage and mobilization of glycogen in mouse liver, and results in neonatal death in C57BL/6J mice." (PMID 33042738, 2020). "In summary, our data demonstrated that the Cavin1 deficiency blocked the bilateral flow between liver glycogen and blood glucose and this led to abnormal storage and mobilization of glycogen in mouse liver and the eventual hypoglycemia in Cavin1−/− mice." (PMID 33042738, 2020). "In the current study, the results show that Cavin1 deficiency causes neonatal death in C57BL/6J mice by dampening the storage and mobilization of glycogen in the liver, which leads to lethal neonatal hypoglycemia." (PMID 33042738, 2020). "Once we cross these mice with Friend Virus B (FVB), the Cavin1−/− mice with 50% FVB background can improve survival with mild neonatal hypoglycemia." (PMID 33042738, 2020). "Without the glucose supply from liver glycogen the blood glucose level in Cavin1‐/‐ pups dropped dramatically and the pups developed lethal hypoglycemia." (PMID 33042738, 2020). "In summary, our data demonstrated that Cavin1−/− mice backcrossed to the C57BL/6J background suffered severe hypoglycemia leading to neonatal death." (PMID 33042738, 2020).
osteosarcoma (2 papers, 2019 to 2021). A usually aggressive malignant bone-forming mesenchymal neoplasm, predominantly affecting adolescents and young adults. "To investigate whether the YAP/TAZ-TEAD transcriptional complex is essential for the expression of CAV1 and CAVIN1 in other cells, we chose the osteosarcoma cell line U2OS." (PMID 30595521, 2019). "In the five-gene signature, we separately evaluated the prognostic potential of CAVIN1, EGFR, SCD3, TES, and MXI1 in osteosarcoma." (PMID 35071320, 2021). "Our results confirmed that SCD3, EGFR, and MXI1 were remarkably up-regulated while CAVIN1 and TES were prominently down-regulated in U2OS osteosarcoma cells compared with hFOB1.19 normal cells." (PMID 35071320, 2021). "Additionally, our experimental results confirmed that SCD3, EGFR, and MXI1 were remarkably up-regulated while CAVIN1 and TES were prominently down-regulated in osteosarcoma cells compared with normal cells." (PMID 35071320, 2021).
aortic aneurysm (1 paper, 2015). A ruptured aneurysm located in the wall of the proximal portion of the descending aorta proceeding from the arch of the aorta. "We also examined caveolin-1 and cavin-3 staining in angiotensin II-induced aortic aneurysms in mice (the cavin-1 antibody was not ideal for staining of mouse tissues)." (PMID 26244347, 2015).
bladder cancer (1 paper, 2020). "Among the six identified survival-related genes, three-genes, EMP1, FGFR1, and CAVIN1, were identified as potential independent prognostic markers for the specific bladder cancer subtype with clinical features described." (PMID 32695477, 2020). "In this particular subtype, the prognosis of bladder cancer can be independently evaluated by a risk model composed of EMP1, FGFR1, and CAVIN1 genes." (PMID 32695477, 2020).
Cyanosis (1 paper, 2020). Bluish discoloration of the skin and mucosa due to poor circulation or inadequate oxygenation of arterial or capillary blood. "We also observed that all the dying Cavin1−/− mice exhibited cyanosis." (PMID 33042738, 2020).
head and neck cancer (1 paper, 2023). A primary or metastatic malignant neoplasm affecting the head and neck.
Hypertension (1 paper, 2014). The presence of chronic increased pressure in the systemic arterial system. "Our work so far demonstrates changes in arterial function in the absence of cavin-1, some of which would favor hypertension and some of which would favor hypotension." (PMID 24658465, 2014).
idiopathic pulmonary artery hypertension (1 paper, 2021). "It is worth noting that endothelial cell‐specific knockout of Cav1 or Cavin1 respectively could directly induce PAH in C57 mice, and CAV1 is a well‐known mutant gene in idiopathic pulmonary artery hypertension (IPAH) patients." (PMID 33755319, 2021).
leukemia (1 paper, 2022). A malignant (clonal) hematologic disorder, involving hematopoietic stem cells and characterized by the presence of primitive or atypical myeloid or lymphoid cells in the bone marrow and the blood. "In addition, we verified the Cavin-1 and Cavin-2 protein levels by Western blotting and indicated they were also lower in leukemia cells than in normal peripheral blood mononuclear cells (PBMCs)." (PMID 35722492, 2022). "Interestingly, low expression of CAVIN1 and CAVIN4 is correlated with poorer outcome but low CAVIN2 expression is associated with a significantly better leukemia prognosis in leukemia." (PMID 35722492, 2022). "Finally, we investigated the prognostic value of CAVIN1, CAVIN2, CAVIN3, and CAVIN4 in leukemia using the R programming language to assess data from LinkedOmics." (PMID 35722492, 2022). "We then used the GEPIA and BloodSpot database to validate the unexpected result and found that high CAVIN2 expression was significantly associated with poorer OS in leukemia (p is 0.037 and 0.022 individually), but the trend was not significant for CAVIN1, CAVIN3 and CAVIN4." (PMID 35722492, 2022). "Consistently, the mRNA level of CAVIN1 was positively correlated with CAVIN2 (R = 0.47, p < 0.05) but not significantly correlated with any other Cavin family members in leukemia." (PMID 35722492, 2022). "The expression of CAVIN1 and CAVIN2 is higher in myeloid leukemia than lymphoblastic leukemia, while CAVIN4 expression is just the opposite in leukemia." (PMID 35722492, 2022).
lymph node metastasis (1 paper, 2023). "Metabolic proteins, such as EHD2 and CAVIN1, were expressed at higher levels in the LN+ group than in the LN- group, and EHD2 and CAVIN1 in the PDF were positively correlated with lymph node metastasis." (PMID 36671802, 2023).
lymphoblastic leukemia (1 paper, 2022). "Cavin-1 and Cavin-2 are often more expressed in myeloid leukemia than lymphoblastic leukemia, but Cavin-4 has the opposite pattern." (PMID 35722492, 2022).
lymphocytic leukemia (1 paper, 2022). "The results show that the transcription of CAVIN1, CAVIN2 and CAVIN3 were significantly lower than in normal samples from healthy donors, and the expression of CAVIN1 in myeloid leukemia is significantly higher than that in lymphocytic leukemia (p < 0.05)." (PMID 35722492, 2022). "We found that the expression level of both CAVIN1 and CAVIN2 in myeloid leukemia is higher than that in lymphocytic leukemia, while the expression of CAVIN4 is higher in lymphocytic leukemia." (PMID 35722492, 2022). "CAVIN1 and CAVIN2 are higher expressed in myeloid leukemias (including AML and CML) than that in lymphocytic leukemias (including ALL and CLL)." (PMID 35722492, 2022).
Obesity (1 paper, 2024). Accumulation of substantial excess body fat. "In addition, Pip treatment can prevent obesity and improve lipid metabolism by regulating adipose tissue expansion (ATE) related genes Sfrp5, MEST, PTRF/Cavin1." (PMID 38547097, 2024).
Right ventricular hypertrophy (1 paper, 2024). In this case the right ventricle is more muscular than normal, causing a characteristic boot-shaped (coeur-en-sabot) appearance as seen on anterior- posterior chest x-rays. "CAV1+/−/Cavin-1+/− mice also showed improved right ventricular hypertrophy and pulmonary vascular remodeling, as observed in CAV1+/− mice." (PMID 38182755, 2024).
squamous cell carcinoma (1 paper, 2012). A carcinoma arising from squamous epithelial cells. "PTRF/cavin-1 showed loss of expression in both adenocarcinoma and squamous cell carcinoma samples." (PMID 22461895, 2012).
tumor (43 papers, 2009 to 2026). "Corroborating with our previous results, there is growing evidence that modulation of CAVIN1 pathways in tumor cells can alleviate the risk of metastasis." (PMID 40269326, 2025). "This is the first study showing PTRF/cavin-1 loss of expression in NSCLC tumor tissue at the protein level." (PMID 22461895, 2012). "On the other hand, tumor samples confirmed loss of PTRF/cavin-1 expression when compared with normal lung using both techniques." (PMID 22461895, 2012). "To investigate the molecular bases of Cavin1 role in CRC recurrence, we made use of a 3D in vitro model, and showed that Cavin1 is expressed by epithelial cancer cells and involved in both tumor cells’ proliferation and invasion." (PMID 40269326, 2025). "LUM+ tumor cells demonstrated a high expression of LUM, GPNMB, and CAVIN1 genes linked to low sensitivity to doxorubicin." (PMID 39685635, 2024). "Conversely, cavin-1 expression in these cells attenuates proliferation, focal adhesion tension, migration, tumor growth and angiogenesis, supporting a role for scaffolds in tumor progression." (PMID 38526159, 2024). "Based above, the relationship between the mRNA levels of CAV1/2 and CAVIN1/2/3 and the tumor stage in LUAD and LUSC were performed using UALCAN." (PMID 37497407, 2023). "The role of Cavin-1 in cancer is controversial as it has both tumor suppression and promotion activities in different cancers or the same type of cancer at different stages of disease progression." (PMID 35722492, 2022). "In relation to the role of non-invasive biomarkers such as exosomes, increased patterns of Polymerase I and transcript release factor (PTRF)/Cavin1 detected in urine exosomes of ccRCC are suggested as biomarkers in this type of tumor." (PMID 35008363, 2021). "Cavin1 serves as a tumor suppressor in prostate cancer, but acts as a tumor promoter in pancreatic cancer." (PMID 33101009, 2020). "We and others have previously documented the expression of Caveolins in RMS and more recently shown the important contribute of Cav-1 and Cavin-1 on tumor growth." (PMID 26086601, 2015). "Interestingly, we observed that CAVIN1 plays a fundamental function in tumor cells, in relation to cell–cell interaction, EMT and invasiveness." (PMID 40269326, 2025). "Importantly, CAVIN1 has previously been studied in the context of tumor progression, and cancer cells expressing higher levels of this protein, as well as other caveolin proteins, tend to be more aggressive and metastatic." (PMID 40269326, 2025). "Also, HT29 cell line was derived from an MSS tumor, which is a better model to test CAVIN1 levels and its link to cancer progression, since our PROT Subtype 1 was mainly comprised of MSS patients." (PMID 40269326, 2025). "The human antibody against CAVIN1/PTRF detected in this study may be clinically applicable as an anti-tumor drug." (PMID 36497311, 2022). "However, details of the mode of binding between Cavin1 and Caveolin1 are scant and the role such binding plays in tumor biology is poorly understood." (PMID 32550897, 2020). "The contradiction between these two studies may be due to the fact that Cavin1 plays different roles in the biology of different tumor cell lines." (PMID 32550897, 2020). "Therefore, Cavin1 overexpressing GL261 enhanced the infiltration of activated microglia inside the tumor." (PMID 32550897, 2020). "Therefore, we decided to explore whether CAVIN1 had a role in epithelial tumors cells, in terms of tumor formation and invasion, or if it was just restricted to the tumor microenvironment." (PMID 40269326, 2025). "Using a mouse model of metastatic TNBC, we identified four new CTC surface markers, AHNAK2, CAVIN1, ODR4, and TRIML2, which specifically stain tumor cells." (PMID 41543394, 2026). "Among these proteins, we focused on Cavin1, which was not only over-expressed in EMT-like tumors, but displayed higher abundance in the entire population of stage III tumor patients that suffered relapse." (PMID 40269326, 2025).
tumor (continued). "The expression of chemoresistance genes has been detected, including KLF4 (doxorubicin and ifosfamide), ULK1, LUM, GPNMB, and CAVIN1 (doxorubicin), and AHNAK2 (gemcitabine) in tumor cells and ETS1 (gemcitabine) in TME." (PMID 39685635, 2024). "We identified six survival-related genes, EMP1, TPM1, NRP2, FGFR1, CAVIN1, and LATS2, found in the DEG analyses of both, tumor-paracancerous and paracancerous-normal differentially expressed data sets." (PMID 32695477, 2020). "PTC and FTC tumours presented a group of common dysregulated proteins including SOD3, ISLR, biotinidase, polymerase I and transcript release factor (cavin-1), TFF3, alpha(B)-crystallin (CryAB), AGR2, tenascin and 14-3-3 gamma." (PMID 27025787, 2016). "NEAT1 enhances the expression of PTRF by interacting with the PTRF/Cavin-1, thereby stabilizing its mRNA, and PTRF activates NF-κB signaling by inhibiting the expression of UBXN1, thereby upregulating the transcription of PD-L1 and promoting the immune escape of tumor cells." (PMID 40384875, 2025). "Since EMT-related clusters included both EMT-binding proteins (CAVIN1, COL6A1 and COL6A3) and EMT-driving partner proteins (CAVIN1 and COL6A1), a heterogeneous population of cells with EMT potential may reside within the tumor that drive metastasis." (PMID 36249004, 2022).
cancer (35 papers, 2011 to 2026). A tumor composed of atypical neoplastic, often pleomorphic cells that invade other tissues. "For instance, AHNAK2 and CAVIN1 have been linked to proliferation and migration in different cancers and AHNAK2 and ODR4 were identified as potential biomarkers for adenocarcinomas." (PMID 41543394, 2026). "The outstanding associations between C-to-U RESs across different cancer types and different ICCs were also impressive, for example, CAVIN1 RESs with CD4+ T cells or M2 macrophages, and VWA8 with M1 or M2 macrophages." (PMID 36969056, 2023). "PTRF, also known as cavin-1, is a protein that has been implicated in a number of human diseases and cancers." (PMID 37322408, 2023). "Similar to CAV1, genetic alterations of CAVIN1 in human cancers are rare, represented by less than 2% mutations and amplifications." (PMID 35158857, 2022). "Interestingly, CAVIN1 levels in cancer cells have also been shown to be associated with multidrug resistance." (PMID 40269326, 2025). "In the future, targeting caveolae-associated proteins, especially CAV1 and CAVIN1, may unravel a new paradigm in the treatment of drug resistance in cancer." (PMID 35158857, 2022). "Exosomes, crucial for intercellular communication, involve Polymerase I and Transcript Release Factor (PTRF or CAVIN1), a potential biomarker in cancers." (PMID 39193389, 2024). "PTRF/Cavin-1 promotes multidrug resistance in MCF-7/ADR cancer cell lines through fortification of lipid rafts, which enhances cancer signal transduction." (PMID 39685635, 2024). "Cavin1 deficiency was shown to impair ROS production induced by organ damage in mice, indicating a potential role for Cavin1 in regulating the redox state of cells in cancer." (PMID 37248872, 2023). "In the majority of human cancers, Cavin-1 is downregulated along with Cavin-2, Cavin-3 and Cavin-4 compared in cancer tissues vs. control tissues." (PMID 35722492, 2022). "Cavin-1, a critical structural component of caveolae, was also found to accumulate around the rear of fast-moving cancer cells in 3D matrix and co-localized with caveolin-1." (PMID 31607653, 2019). "Cavin-1 is a key molecule in caveolae and membrane repair processes and essential for multi-drug resistance responses in cancer cells." (PMID 28498861, 2017). "CAVIN1 is highly expressed in normal prostate stroma but lost during cancer progression." (PMID 35158857, 2022). "In terms of CAVIN family, 24 datasets demonstrated lower expression of CAVIN1 in cancer tissues." (PMID 34513683, 2021). "However, a proportion of fibroblasts migrated rapidly in 3D matrix with similar morphology to cancer cells and showed cavin-1 accumulation at the cell rear." (PMID 31607653, 2019). "PTRF/cavin-1 is essential for multi-drug resistance responses in cancer cells." (PMID 28498861, 2017). "In this perspective, since the recent growing body of literature indicating a cooperation between Cav-1 and the polymerase transcription released factor PTRF/Cavin-1 in cancer progression, it will be certainly important to assess their relative contribution in RMS malignancy." (PMID 24427291, 2014). "As a consequence, therapeutic methods targeting CAVIN1 may induce complications in cancer patients." (PMID 34513683, 2021). "All six selected survival-related genes (EMP1, TPM1, NRP2, FGFR1, CAVIN1, and LATS2) were reported to play a positive role in disseminating cancer cells or invasion in many kinds of cancers." (PMID 32695477, 2020). "In some cancer cells, the coordination between these proteins is lost, resulting in antagonistic effect between CAV1 and cavin-1." (PMID 23272165, 2012). "In contrast, in cancer cells expressing both CAV1 and cavin-1, shorter tubules are visible, indicating that cavin-1 limits the ability of CAV1 to form tubules." (PMID 23272165, 2012). "However, the significance of up-regulated Cavin1 and Cavin3 in TNF-induced inflammation in cancer is yet to be defined." (PMID 37248872, 2023).
cancer (continued). "We found that multiple RESs in CAVIN1 3’UTR were correlated with resting CD4+ memory T cells in at least six cancer types, seven in IGAX 3’UTR with M2 macrophages in at least six cancer types, and one in VWA8 intron with M1 macrophages in six cancer types." (PMID 36969056, 2023). "Interestingly, four proteins that were upregulated by cancer were not detectable at all in the control (Ctrl) hippocampal protein samples, that is, Gpt1, Anillin, Camk1 and Cavin1." (PMID 40172096, 2025). "In addition, 1 SNP was detected in KMT2C, a BC oncogene, and 9 others were detected in or near 10 genes (SERAC1, DAGLB, MACF1, NVL, FBXW4, FANK1, KCTD4, CAVIN1; ATP6V0A1 and ZBTB20-AS1) previously associated with non-BC cancers." (PMID 35589867, 2022). "During the course of these experiments, we determined that A431 cells (similar to several other commonly cancer cell lines such as HeLa cells) do not express Cavin2 but have significant expression of the universal components of caveolae, Cavin1, CAV1, and Cavin3." (PMID 31332168, 2019). "To explore whether regulation of CAVIN1 and CAV1 expression by YAP/TAZ-TEAD is a general phenomenon, we used data from cancer cell line encyclopedia (CCLE) and conducted pairwise bioinformatic analysis of CYR61 and CTGF, CAVIN1, or CAV1 expression, respectively." (PMID 30595521, 2019). "Our data support a role for PTRF/cavin-1, through caveolae formation, as an attenuator of the non-caveolar functionality of Cav1 in Gal3-Cav1 signalling and regulation of focal adhesion dynamics and cancer cell migration." (PMID 25942420, 2015).